CCL2 (C-C motif chemokine ligand 2)
Diseases named in the same sentence as CCL2 in open-access papers (continued):
Sharing a sentence is not in itself a finding about the gene and the disease.
tumor (continued). "Therefore, the finding of enhanced M2 macrophage infiltration in the high CCL2 expression group suggested a potential mechanism by which CCL2 may contribute to tumor progression and therapeutic resistance in the recurrent GBM." (PMID 39030882, 2024). "Similarly, therapeutic blocking of CCL2/CCR2 axis against hepatocellular carcinoma inhibited the recruitment of inflammatory monocytes and tumor-associated macrophages, resulting in the reversal of the immunosuppressive TME and inactivation of antitumoral CD8+ T cell responses." (PMID 38786066, 2024). "Thus, miR‐210‐3p stands out as a significantly upregulated “hypoxamiR” (hypoxia‐associated microRNA), and we reasoned that it might play an essential role in regulating CCL2 expression in the hypoxic tumor microenvironment, and thus affecting TAM abundance." (PMID 35658112, 2024). "For example, both CXCL8 and CCL2 promote the production of inflammatory mediators and the recruitment of immune cells through the activation of the NF-κB pathway, which enhances the inflammatory microenvironment of tumors and the resistance of tumor cells to apoptosis." (PMID 38791448, 2024). "Therefore, TAMs with a low CM ratio may promote tumor progression and immune suppression by upregulating CCL20 and CCL2, which is a potential cause of poor patient prognosis." (PMID 39776914, 2024). "The partial effects of tumoral CCL2 knockdown on SMW indicate that other tumor-derived factors compensate for CCL2 deficiency, which could be identified through unbiased molecular profiling of tumor and muscle tissues." (PMID 38973385, 2024). "It has extensively been reported that these anti-tumour drugs impact the tumour microenvironment (TME), target human tumour-associated macrophages (hTAM), and inhibit the transcription of pro-inflammatory cytokines such as CCL2 (chemokine ligand 2), IL-6, VEGF, CCL3, CCL7, and CCL14." (PMID 38257245, 2024). "Furthermore, in a murine model of HCC on a background of fibrosis, the pharmacological inhibition of TAM recruitment via CCL2 showed a significant reduction in the extent of angiogenesis within tumours and, consequently, tumour progression, as measured by tumour volume." (PMID 39684877, 2024). "Collectively, our work demonstrates cisplatin treatment induces an overproduction of oxPAPC and thus recruits MDSCs infiltration to promote the tumour growth through the MCP‐1/CCL2 and LTB4/LTB4R pathways, which may restrict the effect of multiple chemotherapy." (PMID 37905494, 2024). "For example, necroptosis-induced CCL2 release depends on the activation of the receptor interaction protein 1 (RIP1)/RIP3/mixed lineage kinase-like (MLKL) pseudokinase, which may promote the oncogenic phenotype of tumor-associated astrocyte TAA.LncRNA." (PMID 35854199, 2023). "However, CCL2 has also been shown to decrease tumor cell growth and metastasis." (PMID 36374225, 2023). "Therefore, targeting CCL2/CCR2 is a feasible anti-tumor treatment strategy." (PMID 37138860, 2023). "Therefore, we investigated whether inhibition of CCL2 or M2 macrophages enhances the antitumor immunity of shTRAIL in tumor-bearing humanized mice." (PMID 37605148, 2023). "In addition, PNT favours post-translational modification of specific chemokines and cytokines (e.g. CCL2 and CSF-2) which have been shown to favour the recruitment and infiltration of anti-tumour T cells as well as they critically alter MHC-peptide complex inhibiting T cell activation." (PMID 36161514, 2023). "Importantly, we have previously shown that CRC CAFs, in coculture with tumor cells and monocytes/macrophages, substantially induce CCL2 in both CAFs and macrophages—a process dependent on CAF derived M-CSF expression—and thus generate an enhanced monocyte recruiting microenvironment." (PMID 37460545, 2023).
tumor (continued). "Tumor cells not only secrete high levels of colony-stimulating factor 1 (CSF-1) to independently recruit macrophages but also release the chemokine CCL2 in conjunction with Schwann cells, facilitating the infiltration of inflammatory monocytes via the CCL2/CCR2 axis." (PMID 38099290, 2023). "Therefore, PTX3, under the regulation of DNA methylation, could affect the expression of CCL2 and further regulate pro‐tumour inflammation." (PMID 36872292, 2023). "Furthermore, monocyte chemoattractant protein-1 (MCP-1/CCL2) was also increasingly expressed by the tumor cells one week after irradiation, indicating a higher recruitment of TAMs into the TME and a cross-talking signaling between cancer cells and TAM recruitment." (PMID 37958298, 2023). "In addition, astrocytes express microRNA targeting PTEN, which is transported to tumor cells through exosomes to inhibit the expression of PTEN, thereby activating PI3K/AKT/mTOR pathway, increasing the secretion of CCL2, recruiting myeloid cells, reducing cell apoptosis, and promoting tumor growth." (PMID 37228619, 2023). "Notably, we showed that at the same dose of smTRAIL (8 mg/kg), insensitive tumor CT26 cells secreted more CCL2 and recruited more macrophages than sensitive 4T1 cells, which may support tumor growth." (PMID 37605148, 2023). "Furthermore, CCL2 inhibited adrenomedullin formation in tumor cells through its receptor CCR2." (PMID 36374225, 2023). "Finally, we analyzed the role of endothelial CCL2 in tumor progression under in vivo conditions." (PMID 36374225, 2023). "Furthermore, THEM6 may influence macrophage recruitment and polarization in the tumor microenvironment by regulating CCL2 secretion, which in turn affects macrophage recruitment in the tumor microenvironment." (PMID 38081884, 2023). "Interestingly, 4T1 cells that metastasized to the lung constitutively expressed higher levels of CCL2 than the original 4T1 cells, and intravenous injection of 4T1 cells producing a higher level of CCL2 resulted in increased numbers of tumor foci in the lungs of WT and Ccl2-/- mice." (PMID 37208442, 2023). "However, it appears that the role of CCL2 in tumour development and progression is multifaceted." (PMID 37108548, 2023). "Increasing endothelial CCL2 formation may therefore be a strategy to decrease tumor growth." (PMID 36374225, 2023). "However, CCL2 is responsible for inducing macrophages to play a pro‐tumour role." (PMID 36872292, 2023). "Cxcl2, Ccl2, Ccl3, and Ccl8 can act as chemoattractants for myeloid cell recruitment in tumors, while Csf1, Csf2, and Csf3 are central to controlling the recruitment, proliferation, and differentiation of immunosuppressive myeloid cells, including macrophages and neutrophils in the tumor." (PMID 37138326, 2023). "Since CCL2-neutralizing antibodies inhibit not only TAMs but also all the normal monocyte/macrophages in the body (e.g., bone marrow), which contributes to systemic side effects, we thought to utilize the tumor-homing ability of MSCs and to develop a genetically-engineered cellular therapy." (PMID 36672395, 2023). "The mechanisms underlying KC mobilization have not been elucidated, but tumor-derived macrophage chemoattractants, such as M-CSF and CCL2, could be a clue." (PMID 36821387, 2023). "Taking into account that radiotherapy could increase the production of GM-CSF and CCL2 in lung of tumor-bearing mice, and that GM-CSF is an important mediator in inducing the production of CCL2, we investigated whether G-CSF or GM-CSF could induce macrophages to produce CCL2." (PMID 37268941, 2023). "It is important to know whether disrupting MSC-derived CCL2 affects tumor growth." (PMID 36672395, 2023). "Therefore, the expression of Il6, Nos2, Ccl2, Spp1, Tnf, Acat2, Aox1, Crem, Gls2, Per3, Pink1, Txnip, and Ypel3 was examined in acidosis upon simultaneous transfection with microRNA mimics or antagomirs in two tumor lines in vitro and in vivo." (PMID 38069241, 2023).
tumor (continued). "Indeed, CCL2 was required for these anti-tumor immune effects, as CCL2 blockade reduced NK cell accumulation, abolished tumor regressions, and significantly mitigated the survival benefit and number of complete responders to combined EZH2 knockdown and T/P treatment." (PMID 37142692, 2023). "Data suggest that CCL2 may promote tumor cell proliferation." (PMID 36835050, 2023). "Overexpressed CCL2 in neutrophils might promote its pro-tumor effects." (PMID 38204755, 2023). "Therefore, we believe that MYL9 may affect the tumor immune microenvironment by regulating the secretion of CCL2 and TGF-β1 from CAFs, and is closely related to M2 macrophage infiltration." (PMID 37926835, 2023). "In addition, we show that adrenomedullin acting on endothelial cells further stimulates formation of adrenomedullin in tumor cells by inhibiting the endothelial formation and release of CCL2, which acts as an angiocrine factor to inhibit adrenomedullin expression by tumor cells." (PMID 36374225, 2023). "Moreover, YAP/TAZ mobilize myeloid-derived suppressor cells (MDSCs) and tumor-associated macrophages (TAMs) by upregulating various cytokines, including C-X-C motif chemokine 5 (CXCL5), C-C motif chemokine 2 (CCL2), macrophage colony-stimulating factor 1 (CSF1), and interleukin-6 (IL6)." (PMID 38067201, 2023). "Targeting CCL2/CCR2 may also be a powerful measure for inhibiting tumor-promoting myelopoiesis." (PMID 37415162, 2023). "Therefore, CCL2/CCR2 inhibitors in combination with radiotherapy may be an efficient approach for improving the therapeutic effects of radiotherapy in tumor treatment." (PMID 36845095, 2023). "For example, KRAS-mutation status has been linked to PPARδ-CCL2 expression (involved in M2 macrophage transformation and recruitment), reduced NK cell cytotoxicity by increased expression of HLA-E and PD-L1, and epithelial-mesenchymal transition (EMT), a sensitiser for tumours to NK cytotoxicity." (PMID 36864508, 2023). "Furthermore, the interruption of CCL2 inhibition in a breast cancer model was followed by a rebound of circulating monocytes, leading to increased angiogenesis, metastases, and death in tumor-bearing mice." (PMID 37371612, 2023). "Therefore, taken together, it may be suggested that CVC can be a promising agent to prevent the progression of the tumor through inhibition of the CCR2_CCL2 signaling pathway." (PMID 37325423, 2023). "Notably, CCL-2 can mediate the migration and activation of MDSCs in tumours." (PMID 37497234, 2023). "Bone marrow-derived cells from tumor-bearing animals 3-week post-implantation displayed statistically significant migration, achieving maximum migration of 500% and 334% at a plating concentration of 10ng/mL and 30ng/mL for CCL2 and CCL7 respectively (p<0.0001)." (PMID 36685592, 2022). "Furthermore, the chemokine CCL2 and nucleosome-binding protein HMGN5 were increased significantly since CCL2 plays a key role in tumor inflammation and HMGN5 might be the important regulators of gene expression in cells." (PMID 35774500, 2022). "For instance, hypoxic tumor cells produce exosomes that are highly enriched in immunoregulatory cargos, including proteins and chemokines, such as colony-stimulating factor 1 (CSF-1), chemokine (C-C motif) ligand 2 (CCL2), ferritin H, ferritin L, and transforming growth factor β (TGFβ)." (PMID 36233088, 2022). "However, we cannot decipher whether it results of MYCN direct effect on HLA-gene expression in tumor cells, or from an indirect effect due to CCL2 downregulation, resulting in low immune cell infiltration and inflammation." (PMID 36923280, 2022). "In lung cancer, Fpr2 can inhibit tumor growth in mice subcutaneously transplanted with Lewis lung cancer (LLC) cells by limiting the macrophage response to the tumor-derived chemokine C-C motif chemokine ligand 2 (CCL2) and inhibiting the polarization of macrophage M2." (PMID 36120322, 2022).
tumor (continued). "Furthermore, CAR-Ts engineered to express the chemokine receptor CCR2b, which is the receptor of C-C motif chemokine ligand 2 (CCL2), have exhibited more than ten-fold enhanced migration towards CCL2-secreting tumor cells alongside amplified antitumor capacity in comparison with conventional CAR-Ts." (PMID 35634281, 2022). "Furthermore, in vivo MRTX treatment of 3LL ΔNRAS tumor–bearing mice led to a significant down-regulation of Ccl2 expression in the tumor, suggesting that tumor cells may be one of the main sources of this cytokine in the TME." (PMID 35857848, 2022). "However, the CCL2/CCR2 pathway was described to allow the recruitment of adoptively transferred CD8 T cells within lymphoma murine tumors, and this was associated with tumor growth control." (PMID 36429101, 2022). "Taken Tumor Associated Macrophage (TAM) as an example, the expression of TP73 was significantly positively correlated with a surface marker of TAM—chemokine factor CCL2 (r =0.148, P < 0.001), and another surface marker of TAM—cytokine IL10 (r =0.134, P = 0.003)." (PMID 35756491, 2022). "Additionally, CCL2 has been shown to have both tumor stimulating and antitumor effects." (PMID 35464849, 2022). "To determine whether CCL2 was required for Gata4-mediated tumor suppression, we transplanted KP tet-Gata4 tumor cells into immunocompetent syngeneic hosts and divided mice into control or doxycycline groups with either a CCL2-neutralizing antibody or isotype control." (PMID 35017504, 2022). "Furthermore, examination of CCL2 levels using IHC demonstrated overexpression in the primary tumor as well as in a metastatic lesion of human PDA, where CCL2 was overexpressed starting in early disease and continued to be expressed highly throughout disease progression." (PMID 36256464, 2022). "Moreover, neddylation inhibition was proved to decrease macrophage tumor infiltration through chemotactic cytokine ligand 2 (CCL2) reduction, thus modulates the tumor microenvironment and could be a potent cancer therapy." (PMID 35602593, 2022). "Although studies have investigated the use of a CCL2 antagonist on the recruitment of macrophages and their interactions between other immune cells, no studies have correlated macrophage recruitment to the functional changes in the tumor microenvironment (i.e., hypoxia)." (PMID 35461243, 2022). "In addition to microRNA, CRC can also release type Iγ phosphatidylinositol phosphate kinase (PIPKIG) to trigger PI3K/AKT1/MTOR signaling pathway, promoting TAM recruitment in tumor area through reinforcement of CCL2 transcription, thus providing an appropriate environment for CRC development." (PMID 35186730, 2022). "Thus, LIF and CCL2 might be responsible for high percentage of mesenchymal subtype tumor focus in mGBM and the two cytokines could help diagnosis of molecular subtypes of GBM in histopathological examination." (PMID 34987659, 2022). "In addition, we evaluated whether CCL2 is involved in β-catenin crosstalk between monocytes and tumor cells." (PMID 35562953, 2022). "Interestingly, converse depletion of CCL2 led to a decrease in tumor size and TAM recruitment only in the background of GNA13 loss, but not in GNA13 wild-type tumors, proposing pharmaceutical targeting of CCL2 in GNA13-mutant cancers as a possible therapeutic intervention to be further investigated." (PMID 35027544, 2022). "Because a previous study reported that the suspension of CCL2 neutralizing antibody therapy could lead to rapid tumor recurrence due to monocyte release from the bone marrow and blood vessel formation, we also discontinued Mogamulizumab therapy to investigate the recurrence of tumor in this study." (PMID 35177591, 2022). "In addition, ACKR2 expression was correlated to the expression of its counterpart ligand, i.e., CCL2, but not CCL5 and CCL8, suggesting that ACKR2 downregulation increases CCL2 in the tumor microenvironment to recruit more inflammatory cells and promote inflammation." (PMID 35677043, 2022).
tumor (continued). "Interestingly, expression of CCL2, perhaps more commonly known as MCP‐1, the most important chemokine for macrophage recruitment was increased in both the primary tumor and the lungs providing further support for the relationship between macrophages and tumor growth and metastasis in this model." (PMID 36325601, 2022). "Interestingly, no downregulation of chemokines other than CXCL12 was found by Tranilast administration, though it is well known that CCL2 (MCP-1) is a major chemoattractant for recruiting monocytes, causing increased CCR2-expressing macrophage migration into the tumor site." (PMID 34997450, 2022). "For example, tumor-derived PAI-1 promotes the migration of monocytes and polarizes tumor-associated macrophages (TAMs) towards proinflammatory phenotypes, leading to the production of proinflammatory and angiogenesis-promoting factors such as IL-1, IL-8, CCL2, CCL3, CCL5, and VEGF." (PMID 34912726, 2021). "Additionally, immunotherapy against some specific chemokines such as CCL2 may alter the polyomaviruses-related tumor microenvironment, which needs to be explored by future studies." (PMID 34082771, 2021). "Although large number of studies have confirmed that CCL2 expression in host organs could promote the metastasis, few study discussed how the primary tumor cells regulate CCL2 expression in these remote tissues before tumor cell motility." (PMID 34249913, 2021). "Additionally, VEGF and CCL2 also act as strong chemotactic factors for the infiltration and polarization of TAMs and increased expression of both is positively correlated with a high degree of tumor neovascularization in human invasive ductal breast carcinoma." (PMID 34771482, 2021). "Furthermore, tumor hyperthermia potentiated immune system responses through release of exosomes containing chemokines (CCL2, CCL3, CCL4, CCL5, and CCL20), HSPs, and tumor antigens to the antigen-presenting cells and facilitated tumor cell attack and tumor cell surface modulation." (PMID 34337063, 2021). "Inhibition of CCL2 has been shown to limit early metastatic processes in breast cancer; however, after cessation of therapy, increased metastatic spread is observed due to enhanced recruitment of monocytes to micrometastatic lesions in breast and lung metastasis mouse tumor models." (PMID 33953710, 2021). "Once immune cells were recruited to the tumor lesions, macrophages are extraordinarily abundant and are present in all stages of cancer progression under a gradient of tumor-derived chemo-attractants including CCL-2, tumor necrosis factor (TNF), IL-8, IL-6, VEGF-A, and CSF-1." (PMID 34138315, 2021). "The inflammasome/IL-1 pathway is an important mechanism in the development of BC lung metastasis, as confirmed by the significant reduction of lung metastasis in inflammasome or caspase-1-deficient mice, and may be related to IL-1β-induced expression of CCL2 in macrophages and tumor cells." (PMID 34602858, 2021). "To study whether the association of chemotherapy with the prognosis was independent from the immune markers in the different nodal stage and tumor stage patient groups, we performed multivariate Cox’s regression analyses (adjusted for the immune markers CCL2, CD68, and CD163)." (PMID 33467469, 2021). "Additionally, cycling hypoxia increases CCL2/MCP-1 production in the tumor." (PMID 34639040, 2021). "In orthotopic lung cancer mice model, LM-DOX could migrate to tumor efficiently in response to CCL2, which facilitated the specific delivery of the encapsulated DOX to tumor cells and the production of TNF-α through activating TAMs by LPS anchored on macrophages." (PMID 34834304, 2021). "In the present research, we used CCL2 knockout mice to construct a spontaneous BC metastasis model, and compared with that of normal mice, the proportion of MDSCs recruited in the lungs of tumor-bearing mice was significantly reduced, and the lung metastasis was also greatly reduced." (PMID 34249913, 2021).